MUC4 (mucin 4, cell surface associated)
Diseases named in the same sentence as MUC4 in open-access papers (continued):
Sharing a sentence is not in itself a finding about the gene and the disease.
pancreatic cancer (continued). "MUC4 augmentation of cell cycle progression is also supported by our earlier findings in pancreatic cancer cells." (PMID 23408941, 2013). "Pancreatic cancer cell lines S2.028 and T3M-4 transfected with miR-200c showed a 4.18 and 8.50 fold down regulation of MUC4 mRNA, and 4.68 and 4.82 fold down regulation of MUC16 mRNA compared to mock-transfected cells, respectively." (PMID 24204560, 2013). "Among the interaction partners of the markers, more than one-third has been previously reported as associated with survival or prognosis in pancreatic cancer, including PPARG, MUC4, and SMAD3." (PMID 22615549, 2012). "Our findings will lead to a better understanding of the mechanisms leading to the aberrant expression of MUC4 in pancreatic cancer cell lines." (PMID 22537161, 2012). "Recently, nicotine was shown to induce mucin genes in cancer and that many endogenous molecules like Retinoic Acid (RA) and IFN-γ can induce expression of MUC4 in CD18/HPAF pancreatic cancer cells." (PMID 22537161, 2012). "MUC4-oncotropic viruses or control IgGs-conjugated viruses were then injected in the intra-pancreatic tumors." (PMID 23088623, 2012). "The mucin MUC4 and its membrane partner the ErbB2 oncogenic receptor are potential interacting partners in human pancreatic tumour development." (PMID 22393391, 2012). "The significant overexpression of MUC4 points to an important role for MUC4 in tumor progression, especially in pancreatic cancer." (PMID 22537161, 2012). "This adds to the complexity of MUC4 biological activities in cancer since at least three major signalling pathways are under its control in pancreatic cancer cells." (PMID 22393391, 2012). "MUC4 mRNA was also expressed in the two gastric cancer cell lines in the present study, as shown in the previous study analyzing the pancreatic cancer cell lines by RT-PCR and northen blot analyses." (PMID 23152882, 2012). "Recent studies have shown that knock-down of MUC4 expression reduced pancreatic tumor cell growth and metastasis." (PMID 22537161, 2012). "We find a positive correlation between the binding of E2F1 and STAT1 with MUC4 promoter and its expression in pancreatic cancer cell lines." (PMID 22537161, 2012). "Our studies show that agents that can promote the growth and invasion of pancreatic cancer cells induce the MUC4 gene through multiple pathways and this induction requires the transcriptional activity of E2F1 and STAT1." (PMID 22537161, 2012). "miR-150 directly targets MUC4 in pancreatic cancer cells, an aberrantly overexpressed transmembrane mucin promoting growth, invasion and metastasis." (PMID 22857597, 2012). "In the present study we explored the molecular mechanisms governing MUC4 expression in pancreatic cancer cell lines in response to stimulation with different agents that are known to affect the biology of pancreatic cancer." (PMID 22537161, 2012). "We previously showed that TGF-β1 is a key regulator of MUC4 expression in pancreatic cancer cells via the TGF-βRII/Smad3–4 pathway." (PMID 22393391, 2012). "It thus appears that different signaling components mediate the induction of MUC4 in pancreatic cancer cells depending upon the stimulant." (PMID 22537161, 2012). "Our data also suggests a role in pancreatic tumour growth for ErbB2, while MUC4 is involved in both tumour growth and dissemination." (PMID 22393391, 2012). "Studies in human cells remain scarce and suggest so far a possible role for MUC4 in the biological properties of pancreatic cancer cells." (PMID 22393391, 2012). "We evaluated the transfer of the TK gene by MUC4 oncotropic lentiviruses injected in orthotopically grafted human pancreatic tumor cells." (PMID 23088623, 2012). "Functional studies on MUC4 have provided substantial evidence for its role in the promotion of pancreatic cancer cell growth and metastasis." (PMID 22537161, 2012). "Altogether, these results indicate that both ErbB2 and MUC4 play a role in pancreatic tumour growth in vivo." (PMID 22393391, 2012).
pancreatic cancer (continued). "In this paper, we investigated the role of E2F1 and STAT1 transcription factors on MUC4 regulation in pancreatic cancer cells and found that both the transcription factors can positively regulate MUC4 transcription." (PMID 22537161, 2012). "The antibodies were further tested for their ability to specifically recognize the MUC4 protein in the lysates of MUC4 expressing pancreatic cancer cell lines by immunoblotting." (PMID 21886786, 2011). "Our previous study reveals that MUC4 is aberrantly expressed in ovarian tumors and in pancreatic tumors." (PMID 21521521, 2011). "All the antibodies reactive with the region upstream of the MUC4 TR domain were able to recognize MUC4 in the cell lysates of MUC4-expressing pancreatic cancer cells." (PMID 21886786, 2011). "Another study from our laboratory shows that down-regulation of MUC4 is involved in the suppression of pancreatic tumor cell growth and metastasis." (PMID 21521521, 2011). "Selected clones were characterized by their reactivity toward MUC4 in immunoblotting, immunoprecipitation, immunofluorescence and flow cytometry using pancreatic cancer cells." (PMID 21886786, 2011). "Our recent studies have demonstrated that MUC4 contributes to the chemoresistance in pancreatic cancer cells by activating anti-apoptotic pathways and promoting cell survival." (PMID 21886786, 2011). "The ability of antibodies to detect MUC4 in tumor tissues was tested by immunohistochemical analyses performed on pancreatic cancer tissues." (PMID 21886786, 2011). "The antibodies also reacted with the MUC4 in human pancreatic tumor sections in immunohistochemical analysis." (PMID 21886786, 2011). "Pea3 is a positive regulator of Muc4 expression in pancreatic cancer cells, whilst also acting as a negative regulator of ErbB2." (PMID 20949099, 2010). "It was observed that CFTR was downregulated in pancreatic cancer cells and negatively correlated with MUC4." (PMID 24281201, 2010). "Via its control of the balance between relative expression levels of Muc4 and ErbB2, Pea3 is thought to promote pancreatic cancer cell differentiation." (PMID 20949099, 2010). "IFN-γ and RA can synergize at the transcriptional level to affect MUC4 induction in pancreatic tumour cells." (PMID 24281201, 2010). "The fact that elevated MUC4 expression occurs in the majority (70-80%) of pancreatic carcinomas, most notably at early onset of disease progression, leads to the discussion of MUC4 as a new tumor marker for this deadly disease." (PMID 20553613, 2010). "Here, in this study, we explored the function of MUC4 in development of resistance to gemcitabine in pancreatic cancer cells." (PMID 19738614, 2009). "Anti-apoptotic function of MUC4 in pancreatic cancer cells in response to serum starvation has also been observed earlier in our laboratory." (PMID 19738614, 2009). "In our recent study, we showed that AP-2α is a trans-repressor factor of MUC4 promoter in two well-differentiated pancreatic cancer cell lines that expressed MUC4." (PMID 19672266, 2009). "MUC4 was stably down-regulated in CD18/HPAF pancreatic cancer cells, which express high level of MUC4, by MUC4 siRNA and resulting stable transfectant pool (CD18/HPAF/siMUC4) was quantitated for MUC4 expression by immunoblot analysis." (PMID 19738614, 2009). "Recently, the anti-apoptotic function of MUC4 in pancreatic cancer cells has been observed in our laboratory." (PMID 19738614, 2009). "A schematic model has been proposed to depict the possible mechanism of MUC4-mediated inhibition of apoptosis in pancreatic cancer cells in response to gemcitabine treatment." (PMID 19738614, 2009). "Annexin-V staining showed that MUC4 inhibited gemcitabine-induced apoptosis of CD18/HPAF/Scr pancreatic cancer cells." (PMID 19738614, 2009). "Annexin-V staining and DNA fragmentation experiment demonstrated that MUC4 protects CD18/HPAF pancreatic cancer cells from gemcitabine-induced apoptosis." (PMID 19738614, 2009).
pancreatic cancer (continued). "We have shown that overexpression of MUC4 in pancreatic cancer cells contributes resistance to gemcitabine by activation of an anti-apoptotic pathway." (PMID 19738614, 2009). "In this study, we performed a set of experiments to define the function of MUC4 in the activation of anti-apoptotic pathways in response to gemcitabine treatment of pancreatic cancer cells." (PMID 19738614, 2009). "In conclusion, our data provide the first evidence that MUC4 imparts resistance to gemcitabine in pancreatic cancer cells." (PMID 19738614, 2009). "The MUC4 transmembrane glycoprotein is aberrantly overexpressed in the pancreatic cancer and recently, has been shown to increase pancreatic tumour cell growth by the inhibition of apoptosis." (PMID 19738614, 2009). "Taken together, these findings indicate that aberrant overexpression of MUC4 in pancreatic cancer contributes resistance to chemotherapeutic agent gemcitabine by activation of MUC4-HER2-mediated anti-apoptotic pathway." (PMID 19738614, 2009). "Our results elucidate the function of MUC4 in imparting resistance to pancreatic cancer cells against gemcitabine through the activation of anti-apoptotic pathways and, thereby, promoting cell survival." (PMID 19738614, 2009). "To decipher the molecular mechanisms that govern MUC4 expression in pancreatic cancer, we previously characterised its promoter and identified several consensus binding sites for AP-2 transcription factor." (PMID 19672266, 2009). "In our earlier studies, MUC4 has been shown to increase the phosphorylation of ERK by stabilization of the expression of HER2 in pancreatic cancer cells." (PMID 19738614, 2009). "Using MUC4-knockdown and overexpression pancreatic cancer cell models, we have shown that MUC4 potentiates pancreatic tumour cell growth and metastasis by altering the behavioural properties of the tumour cells." (PMID 19738614, 2009). "The most convincing data come from pancreatic carcinomas, where normal tissue lacks MUC4 and expression increases with the progression of the disease." (PMID 19761616, 2009). "shRNA-mediated knock-down of MUC4 in pancreatic cancer cells showed a decrease in the total levels and phosphorylated form of ErbB2 protein (at Tyr1248) and was shown that overexpression of MUC4 plays a crucial role in stabilising ErbB2." (PMID 18781152, 2008). "Other studies from our lab have shown that MUC4 is involved in pancreatic tumour cell growth and metastasis." (PMID 18665193, 2008). "Our recent studies revealed an overexpression of MUC4 in ovarian and pancreatic tumours, whereas its expression was downregulated in prostate cancer." (PMID 18665193, 2008). "In human pancreatic intraepithelial neoplasia, MUC4 expression increases progressively with advanced dysplasia, and inhibition of MUC4 by antisense RNA suppresses cell growth and metastases in pancreatic cancer cells." (PMID 18475301, 2008). "Overexpression of MUC4 in pancreatic cancer potentiates pancreatic tumour cell proliferation, survival and invasive properties and also interferes with its interaction to extracellular matrix proteins." (PMID 18781152, 2008). "Recently, we have also shown that in pancreatic cancer cells MUC4 interacts with ErbB2 and stabilizes its localization on the cell membrane." (PMID 18781152, 2008). "In pancreatic cancer cells, MUC4 induces ultra-structural alterations and promotes tumour cell proliferation and survival and interferes in the interaction of tumour cells with extracellular matrix." (PMID 18665193, 2008). "Expression of MUC4 resulted in increased growth, motility, and invasiveness of the pancreatic cancer cells in vitro." (PMID 17595659, 2007). "A recent study has shown that MUC4 is a good candidate marker for early diagnosis of pancreatic cancer in fine-needle aspirates, exhibiting a 91% sensitivity and 100% specificity." (PMID 17595659, 2007). "In our previous studies, inhibition of MUC4 expression reduced in vitro growth of pancreatic cancer cells." (PMID 17595659, 2007).
pancreatic cancer (continued). "Overexpression of MUC4 mucin also induces cellular changes and tumour progression of pancreatic cancer cells." (PMID 17595659, 2007). "Expression of mini-MUC4 increased in vitro growth, motility, and invasiveness of the pancreatic cancer cells." (PMID 17595659, 2007). "To understand the precise role of MUC4 in pancreatic cancer, we engineered a MUC4 complementary DNA construct, mini-MUC4, whose deduced protein (320 kDa) is comparable with that of wild-type MUC4 (930 kDa) but represents only 10% of VNTR." (PMID 17595659, 2007). "MUC4 is highly expressed in human pancreatic tumours and pancreatic tumour cell lines; however, its expression is undetectable in the normal pancreas or chronic pancreatitis." (PMID 17595659, 2007). "Stable ectopic expression of mini-MUC4 in two human pancreatic cancer cell lines, Panc1 and MiaPaCa, showed that MUC4 minigene expression follows a biosynthesis and localisation pattern similar to the wild-type MUC4." (PMID 17595659, 2007). "We demonstrate that MUC4 enhances the growth, motility, and invasive properties of pancreatic cancer cells in vitro." (PMID 17595659, 2007). "In conclusion, our data provide evidence supporting the role of MUC4 mucin in the progression of pancreatic cancer." (PMID 17595659, 2007). "Antisense plasmid-mediated down-regulation of MUC4 expression in a pancreatic cancer cell line enhanced adhesion and decreased motility, findings that are consistent with our data." (PMID 15801978, 2005). "The study suggests that the site of pancreatic tumour growth in vivo strongly influences MUC4 and TGFβ2 expression, tumour morphology, and invasiveness of CD18/HPAF cells." (PMID 14760381, 2004). "MUC4 has been cloned from the human trachea and human pancreatic tumours, and the full-length cDNA sequence is known." (PMID 14760381, 2004). "Our earlier study also demonstrates a serum-dependent increase in MUC4 expression in human pancreatic tumour cells." (PMID 14760381, 2004). "A high level of MUC4 transcripts and proteins was observed in the human pancreatic tumour xenografts at an OT site, a site analogous to human pancreas that does not show MUC4 expression, compared to SC sites." (PMID 14760381, 2004). "Here, we investigated the aberrant regulation of MUC4 expression in vivo using clonal human pancreatic tumour cells (CD18/HPAF) grown either orthotopically in the pancreas (OT) or ectopically in subcutaneous tissue (SC) in the nude mice." (PMID 14760381, 2004). "We have made similar observations on a panel of pancreatic tumour cell lines, where a majority of differentiated adenocarcinomas showed higher levels of MUC4 transcripts compared to cell lines derived from poorly differentiated adenocarcinomas." (PMID 14760381, 2004). "Information regarding the role of MUC1 and MUC4 in the growth of primary pancreatic tumours has remained scarce until recently." (PMID 15494719, 2004). "The apomucins MUC1, MUC5B, MUC5AC, and MUC6 are expressed in the normal pancreas; MUC1, MUC2, and MUC4 are upregulated in pancreatic tumours, whereas MUC5B, MUC5AC, and MUC6 are slightly downregulated." (PMID 14760381, 2004). "The clonal human pancreatic cancer cell line CD18/HPAF that expresses a high level of MUC4 mRNA was used for generating human pancreatic xenografts at different sites in nude mice." (PMID 14760381, 2004). "In summary, we believe that this is the first study showing in vivo regulation of human MUC4 expression in pancreatic tumours." (PMID 14760381, 2004). "GALNT6 knockdown in pancreatic cancer cells reduces MUC4 expression and alters cadherin switching from P-cadherin to E-cadherin, suggesting a similar strategy could be effective in lung cancer." (PMID 40655139, 2025).
pancreatic cancer (continued). "Studies have shown that the expression of MUC4 is incrementally increased during the progression of pancreatic cancer and correlates with the activation of Wnt/β-catenin signaling pathways, which are known to interact with MUC4 and contribute to the modulation of the tumor microenvironment." (PMID 40655139, 2025). "We have previously reported on a novel monoclonal antibody (mAb) we designated F5, which was raised against a glycopeptide derived from the tandem repeat (TR) region of Mucin-4 (MUC4), a heavily O-glycosylated protein that is overexpressed in many pancreatic cancer cells." (PMID 40649822, 2025). "For example, MUC4, which belongs to the same family as MUC1, is recognized as a biomarker for cancer metastasis in pancreatic and colorectal cancers, and is also associated with prognosis in pancreatic cancer." (PMID 40909948, 2025). "Several mucins have shown clinical promise, including MUC1 (also known as CA 15-3 and KL-6, in breast cancer), MUC4 (pancreatic cancer), and MUC5 (gastrointestinal, pancreatic, gastric cancers); however, only one is FDA-approved and in clinical use, MUC16, also known as CA125 in ovarian cancer." (PMID 39767713, 2024). "For example, MUC1 and MUC5AC affect E‐cadherin and β‐catenin complexes, thereby promoting the proliferation, invasion, and metastasis of ovarian and gastric cancer cells; in contrast, MUC4 gene deletion in pancreatic cancer cells inhibits tumor progression by regulating apoptosis and cell cycle." (PMID 37666495, 2024). "Moreover, the interaction between MUC4 and Gal-3 increased pancreatic cancer cell binding to endothelial cells, potentially by clustering MUC4 molecules and exposing adhesion molecules like integrins." (PMID 37915694, 2023). "Therefore, targeting the MUC4–Gal-3 interaction is a potential therapeutic strategy to prevent pancreatic cancer metastasis by inhibiting cancer cell adhesion to endothelial cells." (PMID 37915694, 2023). "In addition, TQ can reduce mucin glycoprotein 4 (MUC4) expression in pancreatic cancer cells, contributing to the regulation of differentiation, proliferation, reduced migration of pancreatic cancer cells, and chemoresistance." (PMID 37185722, 2023). "The MUC4-ErbB2 complex can regulate the production of cell cycle inhibitor p27kip1 or cyclinD1 and play an essential role in the biological characteristics of pancreatic cancer cells and the progression of pancreatic cancer." (PMID 35709153, 2022). "A decrease in MUC4 expression is related to an increase in apoptosis, decrease in motility, and reduced migration of pancreatic cancer cells, whereas the Fas-mediated apoptosis of pancreatic cancer cells is related to the initiation of the JNK and p38 MAPK pathways." (PMID 36686732, 2022). "YY1 could suppress the invasion and proliferation of pancreatic cancer cells through MUC4/ErbB2/p38/mef2cMEF2C-dependent mechanism." (PMID 35359580, 2022). "Researchers also found that Human epidermal growth factor receptor-2(HER2) may play an important role in the progression of pancreatic cancer promoted by MUC4." (PMID 35709153, 2022). "MUC4 is a novel tumor antigen for pancreatic cancer immunotherapy." (PMID 35205408, 2022). "Moreover, some studies described miRNAs such as miR-219-1-3p or miR-150 as negative regulators of MUC4 in pancreatic cancer cells." (PMID 34944818, 2021). "Conversely, we hypothesize that MUC4 escapes miR-210-3p regulation during late pancreatic cancer stages since MUC4 is aberrantly upregulated in advanced PDAC even in the presence of high miR-210-3p expression levels." (PMID 34944818, 2021). "Indeed, we observed that MUC4 activates miR-210-3p transcriptional expression via NF-κB pathway modulation and leads to miR-210-3p overexpression in pancreatic cancer cells and tissues." (PMID 34944818, 2021).